AFP (alpha fetoprotein)
Diseases named in the same sentence as AFP in open-access papers (continued):
Sharing a sentence is not in itself a finding about the gene and the disease.
tumor (continued). "Besides, it may downregulate Alpha‐fetoprotein (AFP) and melanoma antigen (MAGE) to promote antigen modulation of tumour cells so as to escape immune surveillance." (PMID 35961680, 2023). "To date, several promising serum tumor markers with the potential for early diagnosis and surveillance of HCC have been proposed of which PIVKA II appears to be the most promising, with recently published data on its performance (alone or in combination with AFP or ultrasonography)." (PMID 36899960, 2023). "Moreover, in subgroup analysis, we found that triple therapeutic regimen was more suitable for the population with characteristics of AFP > 400 ng/mL, diameter < 10 cm, tumor thrombus and no metastasis." (PMID 36254376, 2023). "Based on this prediction model, the low-risk group, consisting of patients with <4 tumors, tumor size ≤10 cm, absence of tumor rupture, compensated liver function, and AFP <400 ng/mL, could benefit most from TACE." (PMID 37346065, 2023). "Several indicators have been shown to be related to HCC prognosis after LRT, including clinical characteristics such as alpha fetoprotein and imaging features such as tumour size, tumour numbers, the presence of nonsmoothed tumour margins, hypoattenuating halos and internal arteries." (PMID 37254089, 2023). "The possible explanation may be due to AFP levels that did not normalize completely, although the tumour had been eradicated." (PMID 37780370, 2023). "AFP, VI, and EHS were negative prognostic factors associated with tumor burden of HCC patients." (PMID 36562786, 2023). "Multivariable analysis showed that alpha-fetoprotein (AFP) levels > 20ng/mL, neutrophils to lymphocyte ratio > 2.25, non-smooth margin, tumor-to-liver signal intensity ratio in the hepatobiliary phase ≤ 0.6, and post-contrast T1 relaxation time > 705 msec were the independent predictors of Ki-67 LI." (PMID 37456233, 2023). "Besides, tumor markers, including CEA, CA19-9, AFP and CA50 were all normal." (PMID 37726737, 2023). "Recently, we identified several novel TCRs specific to the HLA-A2 restricted Alpha-fetoprotein epitope (AFP158) and showed that human T cells engineered with such TCR genes could recognize and kill AFP+ HepG2 tumor cells, which resulted in regression of HCC xenografts in immunocompromised NSG mice." (PMID 37215108, 2023). "According to tumor characteristics, Kaplan-Meier curves revealed that regardless of tumor size (<5 or ≥5 cm), AFP level (<400 or ≥400 ng/mL), and BCLC stage (0–A, B, C–D), the Huaier users had a significantly higher OS rate than the non-Huaier users (all p < 0.05)." (PMID 37251326, 2023). "Multivariate Cox regression analyses revealed that maximum tumor diameter, poor cell differentiation, and APPRI were independent predictors of DFS; while poor cell differentiation, APRI, APPRI, prothrombin time, and alpha‐fetoprotein were independent prognostic factors for OS." (PMID 37492981, 2023). "In the Cox regression model of univariate analysis, the experience of LR, an absence of ascites, a CTP score = 5, an AFP value lower than 400 ng/mL, and a tumor size > 3 cm or a number of tumor nodules ≥ 3 were all associated with better OS (p < 0.05) before PSM." (PMID 36975456, 2023). "Tumor to liver SUV ratio (TLR) of the primary tumor was statistically significant higher in Milan out tumors (p = 0.018), “up-to-seven” out tumors (p = 0.015), grade 3 (p = 0.023), patients with AFP level > 400 ng/ml (p < 0.001) and lesions of a diameter of 5 cm and more (p = 0.007)." (PMID 35451699, 2023). "After three treatment cycles, radiological examination showed no obvious tumor activity, alpha-fetoprotein (AFP) decreased to normal, protein induced by vitamin K absence or antagonist II (PIVKA II) decreased significantly, and the curative effect was evaluated as complete remission." (PMID 38173715, 2023).
tumor (continued). "Laboratory studies demonstrate that RECAF can be used alone as an aspecific tumor marker, because, unlike AFP, it is found on the cell membranes of most types of tumors with a low degree of differentiation (and therefore, it cannot be said to be a universal type of marker)." (PMID 36768863, 2023). "Although the total staging system for HCC, such as the CLIP score and C-reactive protein and AFP in immunotherapy (CRAFITY) score, includes AFP, other scoring systems, such as BCLC staging, JIS, and the ALBI-T score, basically consist of the tumor burden and hepatic reserve function." (PMID 37686624, 2023). "It had no co-relationship with the tumor markers AFP and PIVKA-II." (PMID 37910585, 2023). "Similar to previous findings, the AFP‐producing adenocarcinoma fraction represented only a small fraction of the entire tumor tissue, in which case, traditional bulk sequencing may not be an ideal fit." (PMID 37017469, 2023). "Notably, all baseline characteristics were not different between the DEB-TACE group and the cTACE group, including age, sex, ECOG PS, etiology, tumor distribution, largest nodule size, tumor capsule, portal vein invasion, splenomegaly, Child-Pugh stage, BCLC stage, and AFP (all P > .050)." (PMID 36751709, 2023). "Furthermore, the tumor markers of PHNET patients did not exhibit any distinctive alterations, and in the majority of patients, the tumor markers (namely AFP, CA19-9 and CEA) remained within the normal reference range." (PMID 37492480, 2023). "In the current case, large tumor cells were recognized as standing in a row, and those cells stained positively with immune-histochemical staining MIB-1, CD117 and D2-40, but negatively with alpha-fetoprotein, human chorionic gonadotropin, and human chorionic gonadotropin-β subunit." (PMID 38845730, 2023). "The use of AFP for detecting prenatal lesions is not reliable, as it does not consistently elevate in maternal serum in most cases, regardless of whether the tumor is mature or immature or whether it is covered by skin." (PMID 37686577, 2023). "The survival and recurrence rate of HCC after hepatectomy depends on factors such as tumor stage, maximum tumor diameter, degree of tumor differentiation and, GGT levels, histological grade of metastasis, age of patients, body mass index, and alpha-fetoprotein (AFP) levels." (PMID 37875876, 2023). "Certain forms of AFP, such as FL-AFP and rhAFP, should not be used in therapy as they may stimulate tumor growth." (PMID 36768863, 2023). "In addition, as not all HCCs are AFP(+), it is important to identify additional tumor antigens to target for immunization for cancer prevention studies." (PMID 37040183, 2023). "Therefore, high-dose capecitabine intervention could decrease AFP and CEA expressions in tumor tissues." (PMID 36742145, 2023). "Moreover, several tumor biomarkers, such as carcinoembryonic antigen (CEA), alpha-fetoprotein (AFP), as well as carbohydrate antigen 19 − 9 (CA 19 − 9), are applied in facilitating early diagnosis, reflecting the state of illness, and evaluating postsurgical follow-up of gastrointestinal tumor." (PMID 37308861, 2023). "Thus, the combination of serum DDR1 and tumour DDR1 levels with other monitoring methods, such as alpha fetoprotein (AFP), computed tomography (CT) or magnetic resonance imaging (MRI), might be helpful in forecasting recurrence." (PMID 37007062, 2023). "According to the study results, the possibility of early PD should be considered if patients with AFP level ≥ 20 ng/mL have an increase in AFP level ≥ 30% at 3 weeks or if patients with AFP level < 20 ng/mL have up-to-seven criteria, OUT, implying high tumor burden." (PMID 37296889, 2023). "The latest retrospective study also showed that adjuvant TACE might promote postoperative recurrence, especially for HCC patients without MVI, tumor size ≤ 5 cm and preoperative AFP < 400 ng/ml." (PMID 37293583, 2023).
tumor (continued). "In line with this, recently engineered microparticles (MPs) derived from alpha-fetoprotein (AFP)-overexpressing macrophages loaded with resiquimod (R848@M2pep-MPsAFP) were developed to target and reprogram M2-like TAMs into M1-like phenotypes to ameliorate tumour immunosuppressive microenvironments." (PMID 37894344, 2023). "Consistent with these previous findings, the AFP TCR T cells with c-Jun overexpression from the tumor mass were less exhausted and less apoptotic and were better able to maintain their function of killing target tumor cells and producing more cytokines of IL2 and IFNγ." (PMID 37215108, 2023). "All patients were negative for immunologic series and tumor markers (AFP, CEA, CA199, and CA125)." (PMID 36213633, 2022). "Other prognostic factors such as low AFP level, low number of tumor nodules and small total tumor diameter at baseline, extended post-interventional tumor necrosis, well differentiated tumor grade and lack of microvascular invasion have been shown to reduce post-LT HCC recurrence." (PMID 36438781, 2022). "Patients with prior cancer had better tumor-related profiles than those without prior cancer, namely, the former patients showed a lower proportion of positive AFP levels and vascular invasion, a lower AJCC stage, a smaller tumor size, and a lower stage of tumor grade." (PMID 35257009, 2022). "The results showed that both mouse CD8+ T cells and engineered human T cells could kill HLA-A2+ AFP+ HepG2 tumor cells without targeting normal primary hepatocytes in vitro." (PMID 35002508, 2022). "The present study has a number of limitations including small sample size in each group, retrospective nature of study, significant differences in baseline characteristics of the two groups such as tumor stage, degree of tumor burden and AFP levels and the lack of analysis of toxicity." (PMID 35434518, 2022). "Modifications in the tumor fraction during TACE were related to neoplastic burden and represented a prognostic predictor of progression and a reliable index of response to treatment, thus representing an alternative to commonly used biomarkers such as AFP and the mRECIST system." (PMID 36230569, 2022). "At present, α-fetoprotein (AFP) measurement is the conventional estimated standard for the diagnosis and prognosis of HCC patients; however, the testing effect is not sensitive and specific enough due to the interference of HCC-unrelated factors and tumor heterogeneity." (PMID 36267972, 2022). "One could argue that a YST component had been missed in the biopsy specimen of the initially marker-negative tumor (i.e., alpha-fetoprotein (AFP) below 25 ng/mL and human chorionic gonadotropin (hCG) below 50 UI/L in both compartments)." (PMID 35884617, 2022). "TFx, which quantify the TFx in circulating system, could serve as a biomarker for patients' tumour burden and could real‐time monitor HCC progression, providing a potential alternative strategy aside from clinically applied biomarker AFP and mRECIST assessment system." (PMID 34939323, 2022). "Due to the limitations of AFP as an HCC screening biomarker, novel biomarkers such as AFP-L3%, des-gamma-carboxy prothrombin (DCP), osteopontin, glycosylated proteins, and circulating tumor cells have been discovered and studied as individual and combination testing." (PMID 36533190, 2022). "Based on the fact that the AFP level correlates with the MVI and degree of differentiation, and the PIVKA-II (DCP) level correlates with the MVI and micro-intrahepatic metastasis, these two tumor markers have been frequently selected as surrogate markers of the biological behavior of HCC." (PMID 35053580, 2022). "In order to improve the prognostic efficiency for postoperative HCC recurrence, we assessed the combination of AFP and CA19-9 as a single prognostic indicator, as sensitivity and specificity in tumor diagnosis can be significantly increased by combining two or more serum tumor markers." (PMID 36258212, 2022).
tumor (continued). "However, univariate analysis identified that four radiologic factors (tumor margin, tumor capsule, peritumoral arterial enhancement, and peritumoral hypointensity on HBP) and one clinical variable (AFP) were significantly related to MVI in the training cohort (p <0.05)." (PMID 35574328, 2022). "Patients with younger age, single tumor, lower pretreatment Child–Turcotte–Pugh score, lower pretreatment tumor marker levels (alpha-fetoprotein, protein induced by vitamin K absence-II), and no previous treatment history were more likely to undergo surgical treatment after liver-directed RT." (PMID 35626001, 2022). "However, the decline of AFP was logarithmically linear, and we did not expect residual tumor to be present before the end of JEB." (PMID 36036317, 2022). "Univariate analysis of PFS showed that age >60 years, HCV infection, antiviral time >5 years, absence of previous surgery, maximum tumor diameter >5 cm, presence of PVTT and alpha-fetoprotein (AFP) > 200 ng/mL were associated with progression in patients treated with lenvatinib." (PMID 36703739, 2022). "Furthermore, variation of the AFP SCORE can be easily calculated in clinical practice and could be a relevant preoperative tool for predicting tumor aggressiveness and other related outcomes." (PMID 35401038, 2022). "Similarly, the preoperative gamma-glutamyl transferase to lymphocyte ratio (GLR) has been found to have a significant prognostic value in AFP-negative HCC patients with a single tumor size ≤ 5 cm undergoing resection." (PMID 35395799, 2022). "We particularly lacked information about tumor markers (CEA, Ca19-9, AFP) in approximately 20–25% of our patients, and the precise localization of the tumor due to insufficient documentation, which could be a confounder in our analyses." (PMID 35884968, 2022). "In addition to circulating tumor cells in peripheral blood, some factors released by tumor cells are found in plasma, and a large number of tumor biomarkers is characterized, including CA125 and AFP, of which CA125 is also a sensitive factor in LC." (PMID 36346805, 2022). "While AFP has been utilized to select HCC patients for transplant, despite years of allocation policy changes, the US allocation system continues to take a uniform approach to HCC patients, without discriminating between those with favorable or unfavorable tumor biology." (PMID 36290870, 2022). "The tumor biomarker levels of cancer antigen 15-3 (CA 15-3), cancer antigen 19-9 (CA 19-9), carcinoembryonic antigen (CEA), cytokeratin fragment 21-1 (CYFPRA 21-1), and alpha-fetoprotein (AFP) were significantly higher in individuals with CVD when compared to individuals without CVD." (PMID 36057714, 2022). "In tandem, we also identified cases of significant AFP elevations without malignant components, and we identified confirmatory histopathology on needle biopsy, highlighting the potential limitations of tumor under-sampling as another source of suboptimal treatment for potentially dangerous lesions." (PMID 35205726, 2022). "MVI mainly reflects the biological feature of the tumor, however, we found that despite superiority over other clinical characteristics, the performance of AFP in predicting MVI status is still unsatisfactory, suggesting that AFP cannot fully summarize the biological features of the tumor." (PMID 36464701, 2022). "The nomogram including rim enhancement, tumor capsule, TTPVI, and AST independent predictive factors displayed a better predictive ability which could assist physicians in personalized treatment decision-making for patients with AFP-NHCC." (PMID 35626229, 2022). "Using the AFP rule-out cutoff values for HCC (AFP < 20 ng/dL), 78% of the subjects were correctly classified as having benign PVT, while 100% of the subjects were correctly classified as tumor-in-vein (TIV) when the rule-in cutoff value was used (AFP ≥ 200 ng/dL)." (PMID 35626300, 2022).
tumor (continued). "Finally, According to multivariable analysis, tumor diameter < 5cm, AFP < 400μg/L, single tumor, and absence of micro-/macrovascular invasion, as well as the Child-Pugh grade A, increased the odds of long-term survival following liver resection." (PMID 35155255, 2022). "In addition, tumour markers like alpha-fetoprotein (AFP), Ca125, CA19-9, and carcinoembryonic antigen (CEA) were negative for all patients with elevated LDH in three of them, the highest corresponding to the highest tumour grading using AJCC tumour criteria." (PMID 36475154, 2022). "While exact AFP cutoff values demonstrating the best post-transplant outcomes are not exact, AFP < 15 ng/mL at transplant had similar outcomes irrespective of whether the tumor burden was within or beyond Milan Criteria." (PMID 36290870, 2022). "Furthermore, studies have shown a lack of correlation between prognostic factors such as tumour size as well as tumour number and AFP." (PMID 36233670, 2022). "Moreover, there was no rise of serum tumor markers, including AFP (alpha fetoprotein), CEA (carcinoembryonic antigen), CA125, and CA199, before and 6 years after MSCs infusions." (PMID 36465325, 2022). "Interestingly, in our study, the expression of AFP, YAP, GRP78, and EpCAM was attenuated in the livers from Stk25-/- mice, supporting the importance of STK25 not only in the development of HCC but also in tumor progression." (PMID 34624527, 2022). "However, AFP is not useful in establishing a prognosis for patients with a tumor in the early stages." (PMID 35053564, 2022). "Serum tumor markers alpha-fetoprotein (AFP) and human chorionic gonadotrophin (HCG) were negative." (PMID 34502216, 2021). "The included inflammation indexes (such as the NLR, MLR, PLR, SII, and SIRI) and AFP, which were derived from peripheral blood counts (e.g., neutrophil, lymphocyte, and platelet) and acute-phase proteins [e.g., C-reactive protein (CRP) and albumin], represented enabling tumor characteristics." (PMID 34869272, 2021). "Moreover, analysis of alpha-fetoprotein (AFP) as one of the most important serum tumor biomarkers for HCC is still not satisfactory for the sensitivity and specificity of HCC diagnosis." (PMID 34988221, 2021). "Laparoscopy may be more appropriate if the suspicion is more for benign disease, where tumor markers (including hCG and AFP) are normal." (PMID 34669199, 2021). "Patients initially treated with liver transplantation had the lowest mean AFP level (57 ± 239 IU/ml), no extrahepatic spread and the second smallest diameter of the largest tumor (25; 16–35 mm) after patients which had locoregional ablative intervention (20; 14–30 mm)." (PMID 33537908, 2021). "Finally, subgroup analysis based on tumor stage or alpha fetoprotein concentration was not performed because of the small sample size of MAFLD group." (PMID 35127490, 2021). "The level of these tumor markers in the blood of HCC patients does not correlate with AFP." (PMID 34513063, 2021). "The two regression models both identified AJCC stage, tumor size, grade, surgical therapy and radiotherapy as independent predictive factors of OS and CSS in the non-chemotherapy group, and AJCC stage, tumor size, grade, surgical therapy as well as AFP in the chemotherapy group." (PMID 34887446, 2021). "Clinically, circMET expression was closely correlated with MVI, multiple tumors, the presence or absence of tumor envelope, as well as advanced stages, while SCD-circRNA 2 expression was associated with serum AFP levels, alanine aminotransferase (ALT) and aspartate aminotransferase (AST) levels." (PMID 34540684, 2021). "Moreover, since our studied tumor markers (t-PSA, AFP, CEA, CA125, and CA199) are the most commonly used tumor markers in abdominal and pelvic tumors and play an important role in cancer detection and management, our study results imply an association between tongue fur thickness and cancer." (PMID 34887933, 2021).